PRDX1 (peroxiredoxin 1)
Diseases named in the same sentence as PRDX1 in open-access papers (continued):
Sharing a sentence is not in itself a finding about the gene and the disease.
osteoarthritis (3 papers, 2022 to 2025). A noninflammatory degenerative joint disease occurring chiefly in older persons, characterized by degeneration of the articular cartilage, hypertrophy of bone at the margins and changes in the synovial membrane. "Our results also highlighted that only three central genes—Prdx1, Nfkb1, and Bmp4—were differentially expressed during Mia-induced osteoarthritis, demonstrating a limited overlap in DEGs related to Mia-induced OA." (PMID 40722985, 2025).
osteoporosis (3 papers, 2024 to 2025). A condition of reduced bone mass, with decreased cortical thickness and a decrease in the number and size of the trabeculae of cancellous bone (but normal chemical composition), resulting in increased fracture incidence. "OTUD1 represents an ideal upstream target for indirectly enhancing PRDX1 activity in a bone-selective manner for treating osteoporosis and other bone-related diseases." (PMID 40585986, 2025). "Therefore, strategies to enhance PRDX1 activity, specifically in bone tissue, such as bone-targeted delivery systems, could maximize therapeutic benefits while minimizing systemic side effects, offering a promising avenue for the treatment of osteoporosis and other bone-related disorders." (PMID 40585986, 2025). "Additionally, the effect of PRDX1 in an in vivo osteoporosis model was not examined in this study." (PMID 39720522, 2024).
Sepsis (3 papers, 2016 to 2022). Sepsis is defined as life-threatening organ dysfunction caused by a dysregulated host response to infection. "Although one report demonstrates that Prdx1 deficiency mitigates lethality in an LPS-induced animal model of septic shock, another report indicates an acceleration of death due to LPS-model sepsis in Prdx1-KO animals." (PMID 35052630, 2022). "Thus, further study is needed to elucidate the precise mechanism of Prdx1 in the etiology of sepsis." (PMID 35052630, 2022). "In addition, there are discrepancies between the role of Prdx1 in whole body homeostasis during sepsis." (PMID 35052630, 2022). "In addition to LPS, several endogenous danger-associated molecular patterns (DAMPs), including the newly identified peroxiredoxin-1 (Prdx1), can also interact with CD14/TLR4 and elicit severe sepsis-like response." (PMID 27142532, 2016). "In addition, CIR-miRNAs in comparison to IL-6, CRP, PCT, and free Hb, generally showed more robust correlations with the APACHE II score, while IL-8 and Prdx-1 had significant positive correlation with the APACHE II score in non-infective SIRS, but not in sepsis." (PMID 29459855, 2017).
systemic inflammatory response syndrome (3 papers, 2016 to 2023). SIRS is a serious condition related to systemic inflammation, organ dysfunction, and organ failure. "Prdx1 release during the early phase of ECMO support in cardiogenic shock patients is associated with the development of systemic inflammatory response syndrome and poor clinical outcomes." (PMID 27142532, 2016). "Thus, the objective of this study was to test the hypothesis that Prdx1 possesses prognostic value and instigates systemic inflammatory response syndrome in cardiogenic shock patients undergoing extracorporeal membrane oxygenation (ECMO) support." (PMID 27142532, 2016). "Correlations of circulating inflammatory-relevant microRNAs (CIR-miRNAs) with peroxiredoxin-1 levels in non-infective systemic inflammatory response syndrome (SIRS)." (PMID 29459855, 2017).
Autoimmunity (2 papers, 2022 to 2023). The occurrence of an immune reaction against the organism's own cells or tissues. "Prdx1 and Prdx5 were the hallmark genes of macrophage cluster 1, and these genes were reported to be associated with autoimmunity." (PMID 37534129, 2023).
bladder tumor (2 papers, 2022 to 2023). "In line with our results, the positive expression levels of the PRDX1 in bladder tumor specimens and its association with recurrence and survival rates of UBC patients had been reported." (PMID 37501157, 2023). "Materials and Methods: PRDX1 and PRDX2 expression levels were examined in 119 bladder tumor specimens by immunohistochemistry and in 150 urine samples (case: 100; healthy controls: 50) using ELISA and their association with recurrence and survival of patients was evaluated." (PMID 35812179, 2022).
cerebral infarction (2 papers, 2016 to 2022). An ischemic condition of the brain, producing a persistent focal neurological deficit in the area of distribution of the cerebral arteries. "In the same cohort, we studied the kinetics of PRDX1 at the acute phase of cerebral infarction and its diagnostic performance to identify cerebral infarction of less than 3 and 6 hours." (PMID 27924073, 2016). "Diagnostic performances of PRDX1 levels were defined by an AUC of 69%, Se of 53% and Sp of 86% for identifying cerebral infarction occurring <3 hours, and an AUC of 68%, Se of 49% and Sp of 88% for cerebral infarction occurring <6 hours." (PMID 27924073, 2016). "It is worthwhile emphasizing that patients with LACI, characterized by low volume, present PRDX1 levels comparable to other cerebral infarction subtypes and significantly higher than controls." (PMID 27924073, 2016). "For the purpose of diagnosis it was therefore of interest to assess if PRDX1 levels were significantly different in these patients compared to those with cerebral infarction." (PMID 27924073, 2016). "These first results suggest that PRDX1 levels could be the basis of a new method using biomarkers for determining cerebral infarction onset." (PMID 27924073, 2016). "Peroxiredoxin 1 (PRDX1), an enzyme involved in oxidative stress, has the ability to identify cerebral infarction with a specificity of 86% and sensitivity of 53%, and could be a new biomarker in TIA diagnosis." (PMID 35207321, 2022). "This mainly explains the wide distribution of PRDX1 values in some subgroups and the lack of power to reach significance for cerebral infarction subtypes when comparing biomarker levels from one time window to another." (PMID 27924073, 2016).
Cerebral ischemia (2 papers, 2016 to 2022). Restriction of arterial blood supply to the brain associated with insufficient oxygenation to support the metabolic requirements of the tissue. "Furthermore, it would be of high interest to combine the diagnostic performance of PRDX1 and GST-π along with other proteins released or activated at different times during cerebral ischemia and inflammation." (PMID 27924073, 2016). "Overall, whether their actions are favourable or not, these data support increased levels of PRDX1 during cerebral ischemia." (PMID 27924073, 2016).
colon adenocarcinoma (2 papers, 2017 to 2025). "Western blot analysis showed that PD‐L1 protein levels were significantly decreased in colonic adenocarcinoma tissue from PRDX1‐KO mice." (PMID 41306557, 2025). "In this study, we found that knockout of PRDX1 robustly suppressed AOM/DSS‐induced colonic adenocarcinoma compared with wild‐type C57BL/6J mice, accompanied by highly infiltrated CD4+/CD8+ T cells and reduced CD163+ tumor‐associated macrophages (TAMs)." (PMID 41306557, 2025).
COVID-19 (2 papers, 2020 to 2021). A disease caused by infection with severe acute respiratory syndrome coronavirus 2. "Plasma proteins associated with neutrophil and ROS responses including IL8, CXCL10, and EN-RAGE primarily derived from activated neutrophils, IL6, and PRDX1 were also elevated in lung tissue from patients with COVID-19." (PMID 34648357, 2021).
depression (2 papers, 2011 to 2026). "The other YWHAZ abnormalities were the interactions with RNPS1 and LGALS1 in schizophrenia; the interactions with MYCBP2, PRDX1 or TP1l in bipolar disorder; the interactions with RPLP2 and VIM in major depression; and the interactions with RPLP0 in both schizophrenia and major depression." (PMID 22373040, 2011).
Hepatic steatosis (2 papers, 2019 to 2022). Steatosis is a term used to denote lipid accumulation within hepatocytes. "Several evidences outline a role of PRDXs in the modulation of hepatic functions: PRDX1 expression was decreased in the liver of HFD-fed mice, PRDX4 transgenic mice were resistant to hepatic steatosis, and insulin resistance increased in response to HFD." (PMID 31949886, 2019).
homocystinuria (2 papers, 2021 to 2023). An autosomal recessive inherited metabolic disorder caused by mutations in the CBS, MTHFR, MTR, and MTRR genes. "MMACHC epimutation/PRDX1 mutation analyses should be part of routine genetic testing for all patients presenting with a metabolic phenotype that combines methylmalonic aciduria and homocystinuria." (PMID 34215320, 2021).
kidney cancer (2 papers, 2021 to 2026). Primary or metastatic malignant neoplasm involving the kidney. "The results obtained offer fresh perspectives on the mechanisms underlying the cytotoxic effects induced by gambogic acid, further suggesting that PRDX1 may represent a promising candidate for targeted therapy in the development of novel anticancer agents, notably for the treatment of kidney cancer." (PMID 42237349, 2026). "Increased or decreased levels of PRDXs mRNA expression levels were found among 33 tumor types, such as PRDX1, PRDX2, PRDX4 and PRDX5 increased in several cancer types, while PRDX3 and PRDX6 decreased in there types of kidney cancer (KIRP, KIRC and KICH)." (PMID 34246267, 2021). "Notably, when compared to adjacent or normal tissues, PRDX1, PRDX2, PRDX4 and PRDX5 were significantly up-regulated expression in several cancer types (UCEC, READ, BLCA, BRCA, CHOL, COAD, LIHC, THCA), while PRDX3 and PRDX6 were down-regulated expression in kidney cancers." (PMID 34246267, 2021).
pancreatic ductal adenocarcinoma (2 papers, 2023). An infiltrating adenocarcinoma that arises from the epithelial cells of the pancreas. "PRDX1 deletion has an impact on biological pathways critical to the survival of pancreatic ductal adenocarcinoma cells, as well as STAT3 and autophagy." (PMID 37227568, 2023).
papillary thyroid cancer (2 papers, 2010 to 2015). "In particular, ferritin heavy chain [FHC], peroxiredoxin 1 [PRX1] and 6-phosphogluconate dehydrogenase [6-PDGH] were exclusively upregulated in the tall cell variant of papillary thyroid cancer." (PMID 24281099, 2010).
prostate tumour (2 papers, 2013 to 2017). "Elevated PRDX1 increases prostate tumour vasculature, and shows up‐regulation of angiogenic proteins such as VEGF in the tumour region." (PMID 27653015, 2017).
renal fibrosis (2 papers, 2016 to 2024). A final common manifestation of a wide variety of chronic kidney diseases characterized by glomerulosclerosis and tubulointerstitial fibrosis. "To determine involvement of Prdxs in renal fibrosis, we analyzed the expression pattern of Prdxs isotypes (Prdx1, Prdx2, Prdx3, Prdx4, Prdx5, and Prdx6) in the cortex/outer stripe of outer medulla of UUO kidney." (PMID 26872211, 2016).
scrapie (2 papers, 2012 to 2021). A fatal disease of the nervous system in sheep and goats, characterized by pruritus, debility, and locomotor incoordination. "In experimental in vivo models for neurological disorders such as Huntington′s disease and scrapie, PRDX1 was slightly enhanced." (PMID 23210548, 2012). "Interestingly, PRDX6, a protein that directly networks with our downregulated PRDX1, was shown to be upregulated in scrapie-infected mice and neuronal cell lines and controls expression of PrPC and PrPSc in neuronal cells." (PMID 34394070, 2021). "Although we cannot exclude the possibility that PRDX1, 3 or 4 of the 2-Cys PRDX subgroup were slightly regulated, it is obvious that PRDX6 was strongly affected in scrapie-infected mice brains." (PMID 23210548, 2012).
acute liver failure (1 paper, 2024). Rapid deterioration of liver function causing encephalopathy and coagulopathy. "In APAP-induced acute liver failure patients (GSE74000), IKBKG levels decreased, and Nrf2 target genes were also repressed (i.e., HMOX1, PRDX1, TXNRD1, GPX4, GPX1, GCLC, GCLM, and NQO1)." (PMID 38505605, 2024).
acute myeloid leukemia (1 paper, 2018). Acute myeloid leukemia (AML) is a group of neoplasms arising from precursor cells committed to the myeloid cell-line differentiation. "Cell treatment with sulforaphane also reduced the expression of peroxiredoxin-1, which is increased in almost all acute myeloid leukemia subtypes." (PMID 30581529, 2018).
adenoma (1 paper, 2023). A neoplasm arising from the epithelium. "In vivo images were collected from a spontaneous adenoma in the rectum of a live mouse using fluorescently-labeled peptides specific for Prdx1, EGFR, and ErbB2, respectively." (PMID 37945660, 2023).
Ascites (1 paper, 2011). Accumulation of fluid in the peritoneal cavity (between the layers of the peritoneum that lines the abdomen). "The observed greater level of PRDX1 in TIF relative to ascites is not unexpected for manifold biologically- and analytically-related reasons." (PMID 21980378, 2011).
cardiogenic shock (1 paper, 2016). "The inverse correlation between Prdx1 and ROS levels before the initiation of ECMO signifies that Prdx1 may intensely participate in the intracellular ROS scavenging for cardiogenic shock patients." (PMID 27142532, 2016). "We documented the early time course evolution of circulatory Prdx1, hypoxic marker carbonic anhydrase IX, inflammatory cytokines including IL-6, IL-8, IL-10, MCP-1, TNF-α, IL-1β, and danger signaling receptors (TLR4 and CD14) in a cohort of cardiogenic shock patients within 1 day after ECMO support." (PMID 27142532, 2016).
cervical squamous cancer (1 paper, 2019). "High levels of thioredoxin 1, peroxiredoxin 1 and peroxiredoxin 2 were associated with a poor chemotherapy response in cervical squamous cancer patients." (PMID 31470801, 2019). "Thioredoxin 1, peroxiredoxin 1 and peroxiredoxin 2 are frequently over-expressed in cervical squamous cancer." (PMID 31470801, 2019). "Then, correlation between the expression of thioredoxin 1, peroxiredoxin 1, peroxiredoxin 2 and responses to cisplatin-based neoadjuvant chemotherapy was analyzed in 35 paired tumor samples (pre- and post-chemotherapy) from bulky cervical squamous cancer patients by immunohistochemistry." (PMID 31470801, 2019). "Initially, the expression of thioredoxin 1, peroxiredoxin 1 and peroxiredoxin 2 protein was analyzed in 13 human cervical squamous cancer tissues and their paired adjacent non-cancerous tissues by western-blotting and immunohistochemistry." (PMID 31470801, 2019). "The expression of thioredoxin 1, peroxiredoxin 1 and peroxiredoxin 2 was much higher in cervical squamous cancer tissues compared with paired adjacent non-cancerous tissues by western-blotting and immunohistochemistry." (PMID 31470801, 2019).
chronic pancreatitis (1 paper, 2024). A chronic inflammatory process causing damage and fibrosis of the pancreatic parenchyma. "To explore the role of Hspb1 in SAP, we used Hspb1 knockout (KO) mice, a genetically engineered chronic pancreatitis strain (T7D23A), Anxa2 KO mice, and acinar cell-specific Prdx1 knockout mice." (PMID 38481805, 2024).
colonic adenomas (1 paper, 2024). "The results revealed that the number of colonic adenomas in PRDX1-KO mice was significantly lower than that in WT mice (n = 5, P < 0.05)." (PMID 39430237, 2024).
cystic papillary neoplasms (1 paper, 2017). "In EL-Kras mice, nuclear Prdx1 levels were similar in normal pancreatic tissue and cystic papillary neoplasms (CPN), while cytoplasmic Prdx1 expression was slightly elevated in the cytoplasm of CPNs." (PMID 29190947, 2017).
emphysema (1 paper, 2017). "The increase in the number of mitochondria and the upregulation of the antioxidant Prdx1 in Aldh2*2 Tg mice might also explain its resistance to CS-induced emphysema compared to the WT mice." (PMID 28431562, 2017).
endometriosis (1 paper, 2020). The growth of functional endometrial tissue in anatomic sites outside the uterine body. "Five proteins were found exclusively in the endometriosis groups: PRDX1, H2A type 2-C, ANXA2, ITIH4, and the tubulin α-chain." (PMID 32106990, 2020). "Thus, PRDX1 and ANXA2 are linked to placental/fetal development, while ITIH4 most likely derives from inflammatory monocytes prevalent in endometriosis." (PMID 32106990, 2020).
erythroplakia (1 paper, 2023). "Across control, erythroplakia, and cancer, L-lactate dehydrogenase A chain was upregulated whereas aldehyde dehydrogenase 2, peroxiredoxin 1, heat shock 70 kDa protein 1B, and spectrin alpha chain, nonerythrocytic 1 were downregulated." (PMID 36776920, 2023).
experimental autoimmune encephalomyelitis (1 paper, 2020). An autoimmune demyelinating disease of the central nervous system that is produced experimentally in animals by the injection of homogenized brain or spinal cord in Freund's adjuvant. "In brain specimens from animals with experimental autoimmune encephalomyelitis (EAE), a model of MS, PRDX1 expression was observed in glial cells and a weak PRDX1 signal was found in blood vessels without perivascular infiltrates." (PMID 33265993, 2020).
Familial exudative vitreoretinopathy (1 paper, 2026). Familial exudative vitreoretinopathy (FEVR) is a rare hereditary vitreoretinal disorder characterized by abnormal or incomplete vascularization of the peripheral retina leading to variable clinical manifestations ranging from no effects to minor anomalies, or even retinal detachment with blindness. "Overall, we elucidate a β-catenin/KIF11/PRDX1 axis-dependent ferroptosis mechanism in familial exudative vitreoretinopathy, highlighting ferroptosis-targeting and antioxidant strategies as potential therapies." (PMID 41872221, 2026). "Treatment with the ferroptosis inhibitor ferrostatin-1 or lentiviral overexpression of non-phosphorylatable PRDX1 partially rescues vascular defects in familial exudative vitreoretinopathy-associated mice." (PMID 41872221, 2026).
glaucoma (1 paper, 2015). Increased pressure in the eyeball due to obstruction of the outflow of aqueous humor. "Recent studies on tears from patients with glaucoma have also identified peroxiredoxin 1 as having a possible involvement in inflammation." (PMID 26664739, 2015).
hematoma (1 paper, 2020). A hematoma is a collection of blood from a vascular structure into an extravascular space. "The hematoma volumes and mNSS were also significantly lower in the Prdx1-OE rats." (PMID 32210752, 2020). "In addition, our results show that Prdx1 can reduce the hematoma volume after ICH, its mechanism needs further study, we speculate that Prdx1 inhibits the release of inflammatory factors such as TNF-α, thereby promoting the expression of CD36 and causing the absorption of hematomas." (PMID 32210752, 2020).
Hyperglycemia (1 paper, 2013). An increased concentration of glucose in the blood. "Interestingly in contrast to HUVEC, the gene expression of ROS clearance enzymes, SOD1, GPX1, TXNRD1, TXNRD2, and PRDX1 were upregulated in HMVEC under hyperglycemia." (PMID 24093550, 2013). "Not much detail is available in literature for hyperglycemia-induced gene expression of NFE2L2, TXNRD1, TXNRD2 and PRDX1 in HUVEC." (PMID 24093550, 2013).
inflammatory bowel disease (1 paper, 2022). A spectrum of small and large bowel inflammatory diseases of unknown etiology. "The findings for some of the stool proteins appear consistent with expectations based on the literature, such as the increase in fecal S100A12 in NEC infants and the elevation of mucosal DEFA5, Serpin B1 and peroxiredoxin-1 in NEC infants and/or patients with inflammatory bowel disease." (PMID 36232903, 2022).